RN7SL565P (RNA, 7SL, cytoplasmic 565, pseudogene)
Gene: Miscellaneous RNA gene on chromosome 9 (41,578,903 to 41,579,186, forward strand). Ensembl gene ENSG00000276562.
Homologues: Orthologues: chimpanzee Metazoa_SRP (99% identical), macaque Metazoa_SRP (94% identical). Paralogues in human: RN7SL722P (100% identical), RN7SL787P (99% identical), RN7SL52P (99% identical), RN7SL544P (99% identical), RN7SL763P (99% identical), RN7SL205P (97% identical), RN7SL1 (81% identical), RN7SL2 (81% identical), RN7SL3 (81% identical), RN7SL322P (80% identical), RN7SL230P (80% identical), RN7SL709P (80% identical), and 704 more.